ENSG00000285304 (novel protein)
Gene: Protein-coding gene on chromosome 22 (37,639,693 to 37,666,932, forward strand). Ensembl gene ENSG00000285304.
Genetic constraint (gnomAD): Loss-of-function variants: 41 observed, 59.49 expected, observed/expected ratio (o/e) 0.69, 90% interval 0.54 to 0.89. Missense variants: 688 observed, 789.17 expected, observed/expected ratio (o/e) 0.87, 90% interval 0.82 to 0.93. Synonymous variants: 341 observed, 327.96 expected, observed/expected ratio (o/e) 1.04, 90% interval 0.95 to 1.14.